TNF (tumor necrosis factor)
Diseases named in the same sentence as TNF in open-access papers (continued):
Sharing a sentence is not in itself a finding about the gene and the disease.
Stroke (continued). "The relative protein expression levels of TNF-α and IL-1β were significantly lower in CD200R1-deficient monocytes after stroke compared to WT controls (p ≤ 0.01 and p ≤ 0.05, respectively)." (PMID 30777093, 2019). "Pro-inflammatory microglia dominate during the acute phase after stroke and are characterized by increased tumor necrosis factor alfa (TNF-α), interleukin (IL)-1β, IL-12, and inducible nitric oxide synthase (iNOS) expression amongst others." (PMID 31379859, 2019). "Recently, the TRPV1 antagonist AMG9810 was found to confer neuroprotection by attenuating TNFα production in a rodent model of stroke." (PMID 31223430, 2019). "Tumor necrosis factor, which exists both as a soluble (solTNF) and a transmembrane (tmTNF) protein, plays an important role in post-stroke inflammation." (PMID 31440125, 2019). "In the sub-acute phase of neuroinflammation at 3 days post-stroke, TNFα and IL-10 mRNA expression was substantially elevated in vehicle-treated stroke mice compared to sham mice." (PMID 31138227, 2019). "Intracerebroventricular injection of H19 siRNA reduces infarct volume and brain edema, decreases tumor necrosis factor-α and interleukin-1β levels in brain tissue and plasma, and increases plasma interleukin-10 levels 24 h post-stroke." (PMID 30967760, 2019). "TNF-α can play a dual role in stroke, promoting inflammatory stroke progression on one hand and mediating cerebral tolerance to hypoxia and ischemia on the other." (PMID 30778120, 2019). "Treatment with DS2 significantly decreased circulating IL-6 (0.1 mg/kg, P < 0.01; 1 and 4 mg/kg, P < 0.05), IL-17 and TNF-α levels (P < 0.05 and P < 0.001, respectively following treatment) at 3-days post-stroke." (PMID 31736685, 2019). "For example, spleen cells collected from stroke model mice show a stronger ability to secrete inflammatory cytokines, including TNF-α, IL-6, monocyte chemoattractant protein-1 (MCP-1) and IFN-γ, than those collected from normal mice." (PMID 30700305, 2019). "Targeting TNFα in stroke, therefore, demands careful planning of the time of administration and, ideally, specific inhibitors that only target certain TNFα signaling pathways." (PMID 31544811, 2019). "Etanercept, which is a biologic TNF antagonist, can decrease microglial activation in experimental stroke models and has been used therapeutically in animal stroke models." (PMID 31031649, 2019). "At 4 h post-stroke with clenbuterol treatment, we observed a significant decrease in TNFα gene expression in the stroke condition accompanied by a trend towards an increase in IL-10 gene expression." (PMID 31138227, 2019). "Perivascular macrophages and microglia play an important role in the stroke-induced inflammatory response via production of proinflammatory cytokines (IL1|upbeta TNFα IL6, IL12) and ROS." (PMID 31543756, 2019). "Two important inflammatory mediators of the neuroinflammatory response during stroke rehabilitation are TNF-α and IL-1." (PMID 31031649, 2019). "In contrast to TNFα and IL-1β, IL-6 mainly has neuroprotective effects and plays a major role in body temperature regulation in stroke patients." (PMID 31544811, 2019). "As we had seen at 4 h post-stroke, TNFα mRNA expression was 1.8-fold less in peri-infarct cortex of clenbuterol-treated mice relative to saline-treated mice." (PMID 31138227, 2019). "In stroke patients, serum TNFα is elevated, peaking at day seven post-ischemia and early TNFα levels in the cerebrospinal fluid (CSF) correlate with neurological outcome." (PMID 31544811, 2019). "In the setting of stroke, administration of TNF‐α induced greater gastrointestinal permeability as indicated by a trend towards increased serum levels of orally gavaged FITC‐dextran compared to their corresponding saline‐treated mice." (PMID 31199577, 2019).
Stroke (continued). "The pro-inflammatory cytokine TNFα was strongly reduced early after stroke with clenbuterol treatment and prolonged clenbuterol treatment after stroke led to a suppression of both pro- and anti-inflammatory mediators." (PMID 31138227, 2019). "Tumor necrosis factor-α serum levels are increased within 6 h post-stroke and their levels are maintained for 10 days." (PMID 31291966, 2019). "Our data provide evidence clearly linking RA to adverse stroke-outcome in mice and indicate an approved TNF-α inhibitor as a potential strategy to reduce stroke-burden in this setting." (PMID 30778120, 2019). "Infliximab-treatment of RA mice not only improved arthritic symptoms, but also reduced stroke volumes and neurological dysfunction to WT levels, thereby confirming the relevance of inflammation and in particular, of the cytokine TNF-α." (PMID 30778120, 2019). "The possibility of anti-TNF-α therapies leading to increased infection rates in the setting of stroke, however, would have to be addressed." (PMID 31281252, 2019). "This study demonstrates that L-4F, an economical ApoA-I mimetic peptide, reduces neurovascular and WM damage via reducing proinflmammatory factors RAGE/HMGB-1 and TNFα/PAI-1 in the ischemic brain in db/db T2DM stroke mice." (PMID 31708728, 2019). "Our data show that BDMPs increase the infiltration of leukocytes, microglia/macrophages and neutrophils, and the expression of immune factors IL1β, IL6, and TNF-α in the IBZ of stroke mice." (PMID 31993045, 2019). "Post-mortem studies demonstrate that TNF-α positive cells are observed in brains of severe ischemic stroke patients from 3 days post-stroke, staying positive until 15 months." (PMID 31291966, 2019). "Stroke rats exhibited significantly higher gene expression and protein levels of TNF-α and IL-6 in brain and lung tissue homogenates compared to Sham animals." (PMID 30290827, 2018). "We also show that naloxone enantiomers decrease unstimulated TNF-α secretion from microglia/macrophages isolated from the stroke cortex at day 7 post-stroke." (PMID 29766045, 2018). "As the most studied cytokines in adult stroke, IL-1β and TNF-α have been found to exacerbate brain damage by directly inducing neuronal injury and via consequent production of additional cytokines/chemokines and upregulation of adhesion molecules." (PMID 30405724, 2018). "For example, physiologically relevant levels of TNF-α can induce mitochondrial dysfunction; low (post-stroke) levels of TNF-α rapidly reduce mitochondrial function as indicated by increased caspase 8 activity and a decrease in mitochondrial membrane potential." (PMID 30416436, 2018). "Mice injected with a neutralizing anti-TNF-α antibody after the induction of stroke exhibited a marked decrease in both infarct volumes and mortality." (PMID 29867706, 2018). "It’s reported that increased H19 levels in stroke patients’ blood impaired neurological function and correlated with tumor necrosis factor-α (TNF-α) levels, which was further verified in animal model." (PMID 29651234, 2018). "This idea is further supported by data from our experimental stroke model that showed altered EV counts in plasma from TNF-KO mice compared to WT." (PMID 29807527, 2018). "During stroke, optimal TNF signaling is pivotal for hippocampal neurogenesis, functioning and repair following ischemic insults." (PMID 29751683, 2018). "The pro‐inflammatory cytokines TNF‐α and IL‐6 are involved in the initiation or amplification of the inflammatory response, and higher levels of TNF‐α and IL‐6 have indicated the poor outcome of stroke." (PMID 29484258, 2018). "Although not statistically significant, there was a trend toward a reduction in mortality at 30 days and at 1 year following the event among patients treated with TNFα-i at stroke occurrence compared to the other group." (PMID 30619884, 2018). "Studies have shown that TNF-α, IL-1β, and IL-6 expression is elevated 0.5, 6, and 3.5 h after stroke, respectively." (PMID 30001721, 2018).
Stroke (continued). "It was previously reported that in mouse stroke models, microglia are the main producer of TNF-α while macrophages are of IL-1(b)." (PMID 30405724, 2018). "Expression levels of IL-1β and TNF-α mRNA were elevated at days 1 and 2 after stroke in the vehicle group, but TPPU treatment significantly attenuated expression at day 2 (p < 0.05; n = 6 rats per group)." (PMID 29588470, 2018). "Inflammatory cytokines such as TNF-α, IL-1β, and IL-6 play a role in the induction and pathoprogression of stroke." (PMID 30046341, 2018). "More studies are needed to fully evaluate the relationship between TNF‐α system and vitamin D in stroke patients." (PMID 29484258, 2018). "Knockdown of H19 by siRNA in MCAO rats reduced brain infarct as well as TNF-α and interleukin-1β (IL-1β), and it increased plasma interleukin-10 (IL-10) concentrations 24 h after stroke." (PMID 29651234, 2018). "Consistent with this, expression of IL-1β and TNF-α were significantly reduced by BAY 60-2770 treatment 4 h post-stroke." (PMID 29423274, 2018). "Previous studies in animal models and in stroke patients have shown that continued production of cytokines such as IFNγ, TNFα, IL11, IL-1β, IL-1ra and IL-6 induces and maintains the M1 polarization state." (PMID 30584250, 2018). "Unstimulated macrophages isolated from naïve rats only upregulated expression of TNF-α and IL-6 following exposure to serum from Stroke rats." (PMID 30290827, 2018). "We also subjected TNF knockout mice to experimental stroke (permanent middle cerebral artery occlusion) and validated the effect of TNF inhibition on EV release." (PMID 29807527, 2018). "Stroke-induced monocyte dysfunction resulted in an increase of the interleukin-10 (IL-10) level as well as a decrease of the interleukin-6 (IL-6), tumor necrosis factor-α (TNF-α) and interleukin-1β (IL-1β) levels." (PMID 29636059, 2018). "TNF-α and IL-6 released by astrocytes are among the main pro-inflammatory cytokines implicated in the BBB dysfunction induced by stroke." (PMID 29452577, 2018). "Alveolar macrophages and epithelial and endothelial cells of Sham and Stroke animals were also isolated for evaluation of mRNA expression of interleukin (IL)-6 and tumor necrosis factor (TNF)-α." (PMID 30290827, 2018). "Although baseline production of TNF was modestly elevated in old microglia, young mice exhibited significantly higher microglial TNF expression after stroke, consistent with their larger infarct size." (PMID 29752550, 2018). "MCC950 treatment remarkably reduced TNF-α in stroke animals from 15.74 ± 2.33 to 6.01 ± 2.55 (arbitrary unit) with p value of 0.01." (PMID 29654318, 2018). "Previous reports have shown peripheral monocytes from stroke patients are less able to produce the inflammatory cytokine TNFα upon in vitro stimulation." (PMID 29872438, 2018). "Stroke induces rapid microglial activation and promotes the secretion of a variety of inflammatory mediators including IL-1β, TNF-α, and IL-6." (PMID 29202856, 2017). "Following ischemia, increased SAFR production promotes endothelial activations and increases brain arteries’ permeability, causing the expressions of pro-inflammatory cytokines such as TNF-α, which is an important mechanism involved in stroke size." (PMID 29262656, 2017). "Under pathological conditions such as ischemia, trauma, and stroke, they are rapidly activated, and secrete various cytokines, including tumor necrosis factor (TNF)-α and interleukin-1β." (PMID 27256075, 2017). "Following stroke huge panoply of proinflammatory cytokines that are released in the bloodstream and detectable in the serum, besides IL-6 and TNF-α, also IL-10, IL-4, IL-17, IL-23, and TGF-β increase." (PMID 28373915, 2017). "Stroke patients were found to present with a rapid increase in plasma cytokines resulting in a low ratio of pro-inflammatory tumor necrosis factor alpha (TNFα) to anti-inflammatory interleukin (IL)-10, preceding the appearance of infection." (PMID 28154551, 2017).
Stroke (continued). "Stroke also resulted in an inflammatory response in the fat of obese mice characterised by increased IL-6, TNFα and ICAM-1 expression." (PMID 28798136, 2017). "The increased expression of several pro-inflammatory cytokines, such as TNF-α and IL-8, post-stroke has previously been established." (PMID 29234571, 2017). "IL-17A, produced mainly by activated Th17 cells, can induce the secretion of a variety of stroke-related cytokines, such as IL-6, TNF-α, IL-1β, CXCL1 and CXCL8." (PMID 29262579, 2017). "Tumor necrosis factor, interleukin-1, and interleukin-6 are potent inflammatory cytokines that have been shown to modulate tissue injury in experimental stroke." (PMID 28109273, 2017). "A perfect example in this regard is the fact that ADAM17 inhibitors are often cited as a potential stroke therapeutic under the premise that they could ultimately limit excessive innate-driven inflammation and its associated complications via a reduction in TNFα production." (PMID 29021532, 2017). "The results of our previous study demonstrated that the oral administration of Tao-Hong-Si-Wu Tang (THSWT) attenuated the effects of embolic stroke by inhibiting the expression of TNF-α." (PMID 28168001, 2017). "Blocking TNF-α by using anti-TNF-α neutralizing antibody at 2 h post-stroke can reduce injured volume and improve neurologic outcomes." (PMID 27563878, 2016). "The ratio between the pro-inflammatory TNF- to the anti-inflammatory IL-10 is reduced during the period of the stroke related infection." (PMID 27430328, 2016). "Several studies suggest that the neuroprotective effect of TNF-α following stroke is mediated through TNFR1." (PMID 27586239, 2016). "All together, the present study supports microglial-derived TNF as beneficial and neuroprotective in the acute phase after experimental stroke and as a strong modulator of the neuroinflammatory response at later time points after experimental ischemia." (PMID 27384243, 2016). "In a mid cerebral artery model of stroke, IL-10 administration was found to suppress overexpression of proinflammatory mediators IFNγ and TNFα and reduce lesion volume." (PMID 27022620, 2016). "We demonstrated that a tumor necrosis factor-α–targeted strategy reduces blood pressure and increases litter size in the stroke-prone spontaneously hypertensive rat relative to the control Wistar–Kyoto rat." (PMID 27733586, 2016). "The release of TNF-α is a result of the pathogenesis of disorders such as stroke, Alzheimer’s disease, Parkinson’s disease and severe infections such as meningitis, yet its role during hypoxia is not fully understood." (PMID 26901230, 2016). "Pro-inflammatory mediators (such as IL-6, IL-1β, and TNF-α) contribute to expanding the area of brain injury in the context of stroke." (PMID 27549161, 2016). "We previously showed that TNF is decreased in mTNFΔ/Δ mice compared to mTNFwt/wt controls after experimental stroke." (PMID 28070141, 2016). "In aged wild-type cohorts, female mice also showed increased serum levels of monocyte chemotactic protein (MCP-1), IL-6, and TNF-α than males after stroke." (PMID 27405096, 2016). "Cytokines, including TNF‐α, IL‐1, and IL‐6, are greatly produced by microglia in the brain after experimental stroke." (PMID 27781140, 2016). "Concerning the TNF-α, a significantly increased baseline serum level of TNF-α was found in stroke patients, compared with the control." (PMID 27453748, 2016). "In animal studies of stroke, TNF inhibition via different mechanisms (TNF‐knockout mice or antibodies to TNF or TNF‐binding proteins) has been shown to limit the size of infarct territory (for review, see ref.11)." (PMID 26749043, 2016). "In the current study, a significantly increased baseline serum levels of IL-10 and TNF-α were found in stroke patients (both SAI & nSAI groups), compared to control individuals (P = 0.01 & 0.002, respectively)." (PMID 27453748, 2016).
Stroke (continued). "TNF-α is involved in the process of ischemic injury, and increased IL-6 has been found in the adverse prognosis after stroke." (PMID 27211606, 2016). "Subsequently, we analyzed the correlation between the mRNA expression of Foxp3, IL-10, TNF-α and iNOS with the death and stroke risks." (PMID 27115869, 2016). "Previous studies showed it has a strong inhibitory effect of IL1β, IL6, IL10, TNF and other circulating cytokines, and suggested a potential therapeutic for stroke patients." (PMID 27672514, 2016). "In contrast, macrophages are also a major source of IL-1β, TNF-α and ROS, adding to further inflammatory insult after stroke." (PMID 26742037, 2016). "Complementary to these findings, infusion of neutralizing antibodies against TNFα had an anti-proliferative effect on hippocampal progenitors in a rat model of stroke." (PMID 27480121, 2016). "Production of IL-1, IL-6, IL-10 and TNF-α as a consequence of cerebral insult from stroke can be sensed by the hypothalamus to activate the HPA axis for excessive glucocorticoid release." (PMID 26742037, 2016). "TNF-α is a proinflammatory cytokine, known to be increased during inflammation and can play a role in brain damage from stroke." (PMID 28652929, 2016). "Using LysMcreTNFfl/fl conditional KO mice with specific ablation of TNF in myeloid cells, including microglia, we demonstrate that microglial-derived TNF contributes to TNF-mediated protective effects in experimental stroke." (PMID 27384243, 2016). "CD161+ natural killer cells which produce excess tumor necrosis factor-α accumulate in the placenta of the stroke-prone spontaneously hypertensive rat relative to the Wistar–Kyoto rat." (PMID 27733586, 2016). "Modulating the function of TNF-α and IL-1β has remarkable effects on evolution of the infarct in both experimental and human stroke at the early phase of stroke, corresponding to the therapeutic window (<4.5 h)." (PMID 27688603, 2016). "It was previously demonstrated that the high plasma levels of TNF-α (tumor necrosis factor alpha) stimulated platelet activation in stroke patients." (PMID 27336623, 2016). "Given the contribution of microglia/macrophages to the pathophysiology of stroke, in the present study, we investigated the effect of TNF ablation specifically in myeloid cells on neuroprotection and functional outcome after focal cerebral ischemia." (PMID 27384243, 2016). "In experimental stroke models, administration of neutralizing antibodies to TNF or TNF-binding protein had protective effects." (PMID 27688603, 2016). "In this study, the mRNA expressions of inflammatory cytokines TNF-α, IL-1β, iNOS, and IL-6 in ipsilateral brain cortex were detected at different time points after stroke." (PMID 25889216, 2015). "A significant and rapid up-regulation of TNF-α occurs following focal cerebral ischemia both in animal models and in stroke patients." (PMID 25972779, 2015). "Stroke subjects also showed higher cytokine plasma levels such as TNF-α (28.2 ± 29.3 vs 12.3 ± 4.5 pg/mL; P = 0.0001), IL-1β (7.9 ± 2.6 vs 4.7 ± 1.6 pg/mL; P = 0.0001) and IL-6 (8.2 ± 2.4 vs 4.2 ± 1.5 pg/mL; P = 0.0001) compared to controls." (PMID 25997053, 2015). "Delivery of FTY720 that removes S1P signaling with chronic exposure reduced damage in both initial and S1P-potentiated M/R-challenged brain, while reducing stroke markers like TNF-α." (PMID 26576074, 2015). "Intracerebroventricular injection of TNF-α exacerbates the extent of infarctions in experimental stroke." (PMID 26665003, 2015). "TNF-α has been implicated in the pathogenesis of a wide number of neurological disorders that develop both acutely, as in TBI and stroke, and chronically, as in Alzheimer’s disease and Parkinson’s disease." (PMID 25879458, 2015).